PKP2 (plakophilin 2)
Diseases named in the same sentence as PKP2 in open-access papers (continued):
Sharing a sentence is not in itself a finding about the gene and the disease.
osteosarcoma (3 papers, 2022 to 2025). A usually aggressive malignant bone-forming mesenchymal neoplasm, predominantly affecting adolescents and young adults.
viral infection (3 papers, 2017 to 2021). "We identified a large number of transcripts upregulated consequent to PKP2 deficiency in murine myocytes, inversely correlated with PKP2 abundance in the human transcriptome, and a part of functional pathways associated with inflammatory/immune responses, including those related to viral infections." (PMID 33536940, 2020). "We then determined the effect of PKP2 on viral infection by examining the NP protein expression of WSN/33 IAV." (PMID 28169297, 2017). "Our study further demonstrates that PKP2, a common PB1 interactor, inhibits the IAV polymerase activity, thereby limiting viral infection." (PMID 28169297, 2017). "Consistently, PKP2, FKBP8, TRIM41 and ZMPSTE24 inhibited viral infection of NY/2009 and WSN/33." (PMID 28169297, 2017).
breast carcinoma (2 papers, 2009 to 2021). "PKP2 is reported to facilitate the proliferation and metastatic ability of the breast cancer cell line MDA-MB-231 and the development of tumors in xenograft mouse model." (PMID 34769306, 2021). "Plakophilin 2 (PKP2), for example, is present in breast carcinoma cell lines and is significant as it serves as a marker for the identification and characterisation of carcinomas derived either from or corresponding to, simple, and complex epithelia." (PMID 19223972, 2009).
COVID-19 (2 papers, 2020 to 2022). A disease caused by infection with severe acute respiratory syndrome coronavirus 2. "A total of 6 hub genes were obtained, including: LDHA, TRPA1, PKP2, FBN2, ERO1A, FSCN1, all of which are risk factors for LUAD/COVID-19." (PMID 36157452, 2022).
glioblastoma (2 papers, 2022 to 2023). The most malignant astrocytic tumor (WHO grade IV). "Another study indicated that inhibiting TTN‐AS1 expression could accelerate apoptosis of glioblastoma cells and suppress its malignant biological behaviors, like proliferation, migration, and invasion via the miR‐320b/EGR3/PKP2 axis." (PMID 37528740, 2023).
idiopathic ventricular fibrillation (2 papers, 2018 to 2025). "In the case of Pkp2, variants have been detected in idiopathic ventricular fibrillation and SCD, possible catecholaminergic polymorphic ventricular tachycardia, HCM, DCM and left ventricular non-compaction." (PMID 30619891, 2018).
myocardial infarction (2 papers, 2025). Gross necrosis of the myocardium, as a result of interruption of the blood supply to the area, as in coronary thrombosis. "Regarding the effects of ischemia on the expression of individual proteins, it has been reported that cardiac PKP2 levels are decreased in models of ischemia-reperfusion injury and myocardial infarction." (PMID 41468454, 2025). "Our study extends this paradigm by demonstrating significant PKP2 downregulation across multiple post‐myocardial infarction HF models, suggesting its potential role as a molecular mediator in acquired cardiac pathologies beyond its established genetic associations." (PMID 40979216, 2025). "Notably, PKP2 replenishment therapy markedly improved cardiac function and attenuated fibrotic remodeling in post‐myocardial infarction HF mouse models, thereby providing critical evidence for the therapeutic potential of PKP2 in cardiac disorders." (PMID 40979216, 2025).
Obesity (2 papers, 2023 to 2024). Accumulation of substantial excess body fat. "Accordingly, expression of PKP2 in subcutaneous adipose tissue diminishes in patients with obesity, and normalizes upon mild-to-intense weight loss." (PMID 37607954, 2023). "As the changes occurring in inflamed adipocytes were consistent with a significant loss of SC PKP2 in patients with obesity, we next transitioned our findings to complementary in vitro assays." (PMID 37607954, 2023). "In addition, loss of adipocyte-specific PKP2 expression was observed in patients with obesity, which was linked to premature adipocyte senescence leading to adipose tissue dysfunction." (PMID 39120608, 2024). "Nevertheless, our experiments in vitro, together with the systematic scrutiny of multiple human datasets and observations made in patients with obesity following weight loss, support the connexion between low PKP2 in SC adipose tissue/ adipocytes and the burden of obesity/ inflammation." (PMID 37607954, 2023). "To further substantiate the loss of adipocyte-specific PKP2 in obesity to effectively break the cell cycle and trigger premature senescence, we performed additional assays, together with tests for cell cycle dynamics and cellular senescence in human adipocytes." (PMID 37607954, 2023). "Manipulating PKP2 expressions to restore adipose cellular makeup may therefore constitute an attractive drug-development target to combat obesity-associated inflammatory issues and metabolic complications." (PMID 37607954, 2023). "Thus, discontinued PKP2 in obese/inflamed adipocytes may contribute to the loss of fat cell plasticity, deranged adipose tissue function, and the deleterious consequences of obesity." (PMID 37607954, 2023). "At the crossroad of these events, able to further the molecular pathophysiology of obesity, we found consistent variations affecting the appearance of nuclear protein kinase C alpha (PKCα) in adipocyte cultures in which PKP2 levels were modulated." (PMID 37607954, 2023). "These assays resulted in two distinct patterns for PKP2 gene expression, segregated by fat depot and the obesity state, and matching those of adipogenesis-regulated genes, such as ADIPOQ, PLIN1, and FASN." (PMID 37607954, 2023). "Then, we manipulated PKP2 levels in differentiated adipocytes to gain a better understanding of the impact of decreased PKP2 in patients with obesity, delineating a critical role in fat cell maintenance and adipocyte commitment." (PMID 37607954, 2023). "Altogether, our compiled clinical and biochemical data revealed different expression patterns affecting PKP2 in human fat depots as a surrogate of obesity and impaired metabolism, adipose cell populations (in OM), and adipocyte commitment (in SC adipose tissue)." (PMID 37607954, 2023). "Here the authors uncover a previously unknown defect in cell cycle and adipocyte senescence due to impaired Plakophilin-2 in subjects with obesity." (PMID 37607954, 2023). "We show that PKP2 is canonically expressed in human adipose tissue, specifically in adipocytes, and that diminished PKP2 in subcutaneous fat is an exclusive feature of obesity, returning to the levels found in lean subjects upon mild-to-intense weight loss." (PMID 37607954, 2023). "Our findings connect the expression of PKP2 in fat cells to the physiopathology of obesity, as well as uncover a previously unknown defect in cell cycle and adipocyte senescence due to impaired PKP2." (PMID 37607954, 2023). "Also, the monitoring of PKP2 in SC preadipocytes from female donors with or without obesity showed a higher expression in differentiating “lean” adipocytes, as compared to fat cell progenitors from the female donor with obesity." (PMID 37607954, 2023).
Syncope (2 papers, 2021 to 2025). A transient loss of consciousness (i.e., characterized by a rapid onset, a short duration, and a spontaneous and complete recovery) due to cerebral hypoperfusion. "Of note, patients with variants on the PKP2 gene were in almost all cases symptomatic (9/10) with a very strong arrhythmic onset (2 patients had arrhythmic syncope, 3 had sustained VT and 3 patients had frequent PVC with palpitations)." (PMID 40359643, 2025).
atrioventricular nodal reentry tachycardia (1 paper, 2025). "PKP2-(L)PV carriers were 2:1-matched to control subjects, who had atrioventricular nodal reentry tachycardia but no other cardiac abnormalities." (PMID 41357268, 2025).
autoimmune myocarditis (1 paper, 2019). Autoimmune myocarditis is an autoimmune disease that affects the heart. "Experimental autoimmune myocarditis caused more severe subepicardial fibrosis, cell death, and inflammatory infiltrates in PKP2-Hz hearts than in WT." (PMID 31438494, 2019). "To investigate whether inflammation indeed affects disease progression upon loss of PKP2 expression, we induced experimental autoimmune myocarditis (EAM) in PKP2-Hz and WT mice." (PMID 31438494, 2019). "Here, we examined the influence of exercise, cardiac pressure overload, and autoimmune myocarditis on the progression of ACM using a mouse model of PKP2 haploinsufficiency." (PMID 31438494, 2019).
bladder urothelial carcinoma (1 paper, 2022). "These were additionally narrowed down, based on the similarity between the proteomic profiles and knowledge-based immuno-expression in bladder urothelial carcinoma (green heatmap); ALDH1L1, PKP2, and OGDH were excluded due to the discordancy." (PMID 35402263, 2022).
colon adenocarcinoma (1 paper, 2025). "A recent study proves that downregulation of PKP2 is significantly associated with adverse immune infiltration and poorer survival outcomes in colon adenocarcinoma." (PMID 40796704, 2025).
familial dilated cardiomyopathy (1 paper, 2021). A a genetic form of heart disease that occurs when heart (cardiac) muscle becomes thin and weakened in at least one chamber of the heart, causing the open area of the chamber to become enlarged (dilated). "In the Netherlands, pathogenic variants in the plakophilin‐2 (PKP2) and phospholamban (PLN) gene are the most prevalent genetic predispositions for familial dilated cardiomyopathy (DCM) and arrhythmogenic cardiomyopathy (ACM)." (PMID 33528799, 2021).
gastric adenocarcinoma (1 paper, 2011). "The results of this study suggest that loss of PKP2 and PKP3 proteins may have significant role in the prognosis of gastric adenocarcinoma, however further invastigation including larger case series is needed." (PMID 21194493, 2011). "In summary, present study has identified the significantly decreased PKP2 and PKP3 immunoreactivity in gastric adenocarcinoma." (PMID 21194493, 2011).
inflammatory skin disease (1 paper, 2021). Inflammatory skin disorders covers a broad category that includes many conditions ranging in severity, from mild itching to grave medical health complications These disorders are common in people of all ages and races. "When we compared PSO vs. AD to evaluate desmosome profiling similarities in inflammatory skin diseases, we found that DSG4, DSP, DSG2, and PKP2 displayed less than a two-fold difference in gene expression." (PMID 33995349, 2021).
Insulin resistance (1 paper, 2019). Increased resistance towards insulin, that is, diminished effectiveness of insulin in reducing blood glucose levels. "Desmoplakin (DSP), CXADR, and PKP2 are novel biomarkers for the development of insulin resistance." (PMID 30678306, 2019).
ischemic cardiomyopathy (1 paper, 2022). Ischemic cardiomyopathy is a cardiomyopathy in which a weakness in the muscle of the heart due to inadequate oxygen delivery to the myocardium with coronary artery disease being the most common cause. "Therefore, further studies are warranted to assess the applicability of using the expression of αT-catenin and plakophilin-2 to differentiate patients with non-ischemic cardiomyopathy rather than ARVC." (PMID 35628349, 2022).
Left ventricular noncompaction cardiomyopathy (1 paper, 2018). Left ventricular non-compaction (LVNC) is characterized by prominent left ventricular trabeculae and deep inter-trabecular recesses. "Studies have also provided further evidence suggesting that PKP2 mutations may impact left ventricular cardiomyopathies, including a recent case report that identified a pathogenic PKP2 deletion in two siblings with left ventricular noncompaction cardiomyopathy." (PMID 29288195, 2018).
metastatic tumors (1 paper, 2021). "Interestingly, immunohistochemical results showed that PKP2 expression was more robust in metastatic tumors than in non-metastatic tumors, suggesting that PKP2 plays a potential oncogenic role in the development of oral cancer." (PMID 34203070, 2021).
myeloma (1 paper, 2015). "It is also noteworthy that the 37 top deregulated genes were enriched for the myeloma “stem cell” gene set, including NUDT11, PKP2, ROBO1, AGAP1, NAP1L3 and EPDR1, indicating that “stemness” may play an important role in determining high risk behavior." (PMID 24913504, 2015). "Notably, six of the top deregulated genes (NUDT11, PKP2, ROBO1, AGAP1, NAP1L3 and EPDR1) were recently identified as “stem cell” genes in myeloma." (PMID 24913504, 2015).
Myocardial fibrosis (1 paper, 2025). "This trend was corroborated by a quantitative analysis of collagen fibers in Masson's trichrome‐stained cardiac tissues, suggesting that Pkp2 knockout exacerbates myocardial fibrosis and contributes to HF progression." (PMID 40979216, 2025).
oral cancer (1 paper, 2021). "However, further studies are needed to determine how PKP2 is involved in oral cancer metastasis." (PMID 34203070, 2021).
rectal cancer (1 paper, 2022). A primary or metastatic malignant neoplasm that affects the rectum. "Our present study found that PKP2 was downregulated in rectal cancer tissues compared with the adjacent normal tissues." (PMID 35109912, 2022). "We also developed a two-gene signature (TSTA3 and PKP2) to predict the prognosis of rectal cancer, which was shown to be an independent prognostic indicator through multivariate Cox analysis." (PMID 35109912, 2022). "Low PKP2 expression was correlated with a poor prognosis, indicating a distinct role of PKP2 in rectal cancer development, which needs to be further investigated." (PMID 35109912, 2022). "Our study identified two novel glycolysis-related genes (PKP2 and TSTA3) associated with the prognosis of rectal cancer patients, and further established a risk model based on two novel glycolysis-related genes to effectively predict the prognosis of rectal cancer patients." (PMID 35109912, 2022). "Besides, the exact biological functions of the predictive genes, PKP2 and TSAT3, remain unclear in rectal cancer and need to be elucidated in our subsequent studies." (PMID 35109912, 2022).
Skeletal myopathy (1 paper, 2021). "Previous studies show that the homozygous deletion mutation of PKP2 lead to LVNC and rapid HF, whereas the heterozygous DES p.A337P (NM_001927.3, c.1009G>C) induces LVNC and skeletal myopathy." (PMID 34819141, 2021).
soft tissue tumor (1 paper, 2010). "We also emphasize the various plakophilin-2-positive plaques in AJs (coniunctiones adhaerentes) connecting proliferatively active mesenchymally-derived cells, including interstitial cells of the heart and several soft tissue tumor cell types." (PMID 20671973, 2010).
type 2 diabetes (1 paper, 2022). "Moreover, three more variants were found in subject A, two VUS in the genes APOB and PKP2, and one likely pathogenic variant in the gene GCKR; this variant has been associated with a higher risk of type 2 diabetes." (PMID 36426223, 2022).
viral myocarditis (1 paper, 2020). Myocarditis that is caused by an infection with a viral agent. "The degree of convergence strengthens the notion that alterations in PKP2 can yield some (not all) of the clinical manifestations of viral myocarditis and that this response can be independent of the actual presence or exposure to a pathogen." (PMID 33536940, 2020).
cancer (19 papers, 2009 to 2026). A tumor composed of atypical neoplastic, often pleomorphic cells that invade other tissues. "Among those, the high expression of plakophilin 2 (PKP2) has been reported to be associated with several human cancers." (PMID 36016607, 2022). "As PKP2 is originally an activator for cancer metastasis, the mutation of PKP2 can be a hyperactive variant." (PMID 27625789, 2016). "PKP2 has been linked to cancer malignancy by several clinical and histological analyses." (PMID 34769306, 2021). "PKP2 could be associated with N-cadherin in adherens junctions in cancer cells and involved in immortalization of mesenchymal stem cells." (PMID 22860071, 2012). "PKP2 promotes the growth, division, and migration of cancer cells through activating the EGFR signaling pathway in LUAD cells." (PMID 37920207, 2023). "Increased PKP2 expression was also related to a malignant phenotype and poor prognosis in some cancers." (PMID 35109912, 2022). "What’s more, PKP2/3 and their closely related genes participated in cytokine-mediated signaling pathway, receptor signaling pathway, pathways in cancer and other signal pathways." (PMID 33088217, 2020). "All of the results suggest that MTs of ADPGK, PCGF6, PKP2, NUP93 and SLC22A5 can be the driver mutations controlling the cancer metastasis via affecting the EMT pathways where Snail, Claudin-1 or ZEB1 is involved." (PMID 27625789, 2016). "PKP2 is an activator of epidermal growth factor receptor, and its overexpression is related to cancer malignancy." (PMID 27625789, 2016). "We identify driver mutations in ADPGK, NUP93, PCGF6, PKP2 and SLC22A5, which are verified to enhance cancer cell migration and prompt metastasis with in vitro experiments." (PMID 27625789, 2016). "Some are supported as important in linking inflammation and cancer, for example PKP2, DSG2 and DSC2." (PMID 26489668, 2015). "But as far as we know, the mechanism of PKP2 in cancer is still unclear." (PMID 33403045, 2021). "At the pan-cancer level, most signaling pathways, particularly PKP4, PKP2, JUP, and CTNND2, showed high levels of activation in the Hormone AR signaling pathway, but consistent inhibition of apoptosis, cell cycle, and DNA damage responses." (PMID 37924160, 2023). "The expression of different catenin molecules in different cancer tissues was inconsistent, and several molecules, including PKP3, PKP2, PKP1, and JUP, were overexpressed in several cancer tissues." (PMID 37924160, 2023). "For example, a module containing gene DSG2, PKP2 and DSC2, is served as both inflammation and cancer module." (PMID 26489668, 2015).
cardiac disease (14 papers, 2013 to 2026). "Although the cerebrovascular relevance of PKP2 variants remains uncertain, their association with arrhythmogenic cardiac disease prompted ongoing cardiac follow-up and family screening." (PMID 41769495, 2026). "His sons (III-2, III-3) carry only the PKP2 variant and remain asymptomatic, suggesting a lower risk of severe cardiac disease." (PMID 41287789, 2025). "Alterations in the levels of plakophilin 2 but also its mutation either directly lead to cardiac diseases or at least are correlated with cardiac diseases (reviewed in3)." (PMID 30948763, 2019). "The other findings were pathogenic variants in genes causing severe heart disease (ACVRL1, PKP2 and SCN5A)." (PMID 40620702, 2025). "To conclude, our data support the notion that PKP2 gene therapy holds promise for improving the clinical outcomes of patients with ACM with PKP2 haploinsufficiency, and reinforce the promise of gene therapy for tackling heart disease." (PMID 38665939, 2023). "Moreover, two patients with a PKP2 variant and an aRVi-ECG had a ‘second aetiology’, namely, ischaemic heart disease." (PMID 40832996, 2025). "While this possibility is likely, our data from the GTEx analysis indicate that the relation between PKP2 transcript abundance and the abundance of transcripts involved in the inflammatory/immune response can be documented independently from the existence of a cardiac disease phenotype." (PMID 33536940, 2020). "Notably, truncating variants in genes such as TTN, FLNC, DSP, PKP2, and MYH7 were frequently reported, particularly in young decedents with no significant history of cardiac disease." (PMID 41374444, 2025).